RPS6KB1 (ribosomal protein S6 kinase B1)
Diseases named in the same sentence as RPS6KB1 in open-access papers (continued):
Sharing a sentence is not in itself a finding about the gene and the disease.
dementia (1 paper, 2025). Loss of intellectual abilities interfering with an individual's social and occupational functions. "Sex difference was evident for the association between RPS6KB1 and all-cause dementia, with stronger association in men (P for interaction = 0.037)." (PMID 40092369, 2025). "Combining NEFL and RPS6KB1 with other predictors yielded high predictive accuracy (area under the curve = 0.871) for incident all-cause dementia." (PMID 40092369, 2025). "The increased dementia risk that RPS6KB1 poses for men, however, warrants further investigation." (PMID 40092369, 2025). "There was evidence supporting a sex difference in RPS6KB1 (P for interaction = 0.037), with higher level of RPS6KB1 was associated with a greater risk of dementia in men [HR (95% CI): 1.54 (1.24, 1.91)], but the effect was smaller in women [HR (95% CI): 1.21 (1.02, 1.43)]." (PMID 40092369, 2025). "Future studies are needed to validate the findings on RPS6KB1 in relation to dementia risk." (PMID 40092369, 2025). "The eXtreme Gradient Boosting machine learning algorithm also identified RPS6KB1, NEFL, and KIM1 as the most important protein features for predicting future all-cause dementia." (PMID 40092369, 2025).
kidney cancer (1 paper, 2017). Primary or metastatic malignant neoplasm involving the kidney. "In spite of the detected rate of p-RPS6KB1 in kidney cancer was as high as 92% (60/65), no prognostic value was found." (PMID 28792981, 2017).
periodontitis (1 paper, 2025). An acute or chronic inflammatory process that affects the tissues that surround and support the teeth. "EV-derived miR-128-3p from LPS-induced periodontitis may cause renal inflammation and be mediated by the Rps6kb1, Tgfbr1, and Acvr1 genes through the TGF-β signaling pathway." (PMID 41440335, 2025).
rotator cuff tear (1 paper, 2018). "There were 2 common genes, namely, Rps6kb1 and gelsolin, which displayed commonly regulated expressions in the 3 categories (aging, apoptotic process, and muscle atrophy) of our interest that are known to be associated with muscle degeneration and atrophy after a rotator cuff tear." (PMID 30671462, 2018).
tumor (577 papers, 2000 to 2026). "To elucidate the underlying molecular mechanism by which miR-30e serves as a tumor suppressor in cancer cells, we used bioinformatics tools to identify its potential target(s), and predicted that RPS6KB1 was a potential target of miR-30e." (PMID 34727092, 2021). "These authors observed an unexpected significant down-expression of some Akt-regulated genes such as RPS6KB1 in their PIK3CA-mutated tumor series, but a normal level of AKT1 and mTOR transcripts." (PMID 21209903, 2010). "RPS6KB1 is well demonstrated to be up-regulated in PCa and associated with tumor growth and stage." (PMID 34873618, 2021). "There was a statistically significant association between RPS6KB1 amplification and high P70 S6 kinase protein expression (P=0.0004), with 41% of the amplified tumours (FISH) exhibiting high PS6K expression, and overexpression of PS6K was associated with poor survival (P=0.0083) as well." (PMID 15083183, 2004). "The results show that BRAF, CDKN1A, DIABLO, PEA15, ERRFI1, and RPS6KB1 are highly expressed in tumor cell lines, which is the same as in the TCGA database." (PMID 39239554, 2024). "Ribosomal protein S6 kinase B1 (RPS6KB1) was weakly or moderately positive in normal renal tissues according to CAB018346 staining but moderately or strongly positive in tumor tissues." (PMID 37056387, 2023). "In vivo experiment showed that miR-30e overexpression significantly inhibited tumor growth and decreased RPS6KB1 expression in xenografts." (PMID 34727092, 2021). "Our results here showed that miR-30e suppression and RPS6KB1 upregulation were important in cell migration, colony formation and tumor growth of cancer cells." (PMID 34727092, 2021). "RPS6KB1 expression decreases in the presence of Nexrutine (Nx), a natural compound that inhibits PCa tumor growth in combination with radiotherapy." (PMID 34873618, 2021). "In EC, high expression of RPS6KB1 in tumor tissues indicated poor prognosis of patients with less survival rate." (PMID 34727092, 2021). "Consistent with tumor growth results, the protein levels of RPS6KB1 in tumor tissues from miR-30e overexpression group were much lower than those from miR-NC group analyzed by Western blotting assay." (PMID 34727092, 2021). "Staining scores for RPS6KB1 and p-RPS6KB1 expression in tumor tissues were between 0 and 9, with 81.25% (130/160) and 61.25% (98/160) cases divided into the positive group (no less than 3 scores)." (PMID 28792981, 2017). "Particularly, highly phosphorylated RPS6KB1 (p-RPS6) and RPS6 (p-RPS6) were linked to noticeably lower overall survival rates, suggesting that mTOR pathway activation might be involved in tumor aggressiveness." (PMID 40002868, 2025). "Experimental knockdown of SRSF1 or the RPS6KB1 splice variant induced by SRSF1 in a NSCLC cell line with high SRSF1 expression inhibited colony formation in vitro; and the former also inhibited xenograft tumor growth in vivo." (PMID 34065983, 2021). "In the search of molecular mechanism of miR-30e suppression, we found that RPS6KB1 is a direct novel target of miR-30e, which may be important for tumor development." (PMID 34727092, 2021). "The phosphorylation level of RPS6KB1 was decreased by using inhibitors, which could greatly reduce the volume of tumor cells." (PMID 32325903, 2020). "These include RPS6KB1, APPBP2, and PPM1D that also showed strong association between amplification and increased expression in our primary tumour material." (PMID 17353917, 2007). "In all, 9% of the tumours showed amplification of the RPS6KB1 gene." (PMID 15083183, 2004). "Moreover, RPS6KB1 (p70S6) is highly expressed and phosphorylated in tumor cells." (PMID 32325903, 2020). "TalaA downregulated the phosphorylation of a series of transcription factors, including JUN, NFATC1, EIF4EBP1, ABL, RPS6KB1, and EIF4ENIF1, most of which play pivotal roles in cell proliferation and tumor progression." (PMID 37866481, 2023).
tumor (continued). "SFTPC protein levels were downregulated in tumor tissues, whereas PI3K, p-PI3K, AKT, p-AKT, mTOR, p-mTOR, RPS6KB1, and p-RPS6KB1 protein levels were upregulated." (PMID 37955668, 2023). "Several investigations found that TRIM44 facilitates tumor development through activation of the AKT/mTOR signaling pathway, including phosphorylated P70S6K (also known as RPS6KB1) in several cases." (PMID 35855640, 2023). "It has been found that RPS6KB1, BRIP1, TRIM37, PPM1 D and other tumor-related genes are located in this region." (PMID 34659555, 2021). "Growing evidence suggests that RPS6KB1 and RPS6, two key proteins in the mTOR pathway, as crucial drivers of tumor onset, progression and BRAFi resistance." (PMID 33082316, 2020). "To ascertain if the expression levels of RPS6KB1, RPS6 and IRS-1 proteins varied based on stage of CMM, we used 42 tumor samples (stage I–IV) and 5 normal skin tissues." (PMID 33082316, 2020). "Our observation of RPS6KB1 and RPS6 hypophosphorylation could also relate to DNA damage since DNA damage suppresses S6K1-mediated RPS6 phosphorylation in various tumour cells." (PMID 41253884, 2025). "Additionally, this article discusses VMP1 gene fusions, especially with ribosomal protein S6 kinase B1 (RPS6KB1), shedding light on potential implications for tumor malignancy." (PMID 38612567, 2024). "The proteins RPS6KB1 (70 kDa, polypeptide 1, also called S6K) and EIF4E‐BP1 (also called 4E‐BP1), which take part in cell proliferation and may be useful as activity pathway markers in human tumours, are the two most relevant downstream effectors of Mtor." (PMID 34854221, 2022). "Furthermore, four genes (MAP2K1, EIF4EBP1, MAPK8, and RPS6KB1) were enriched in ERBB signaling pathway, required for GBM stem cell proliferation, and three genes (MAP2K1, MAPK8, and RPS6KB1) were enriched in NFAT pathway, promoting tumor angiogenesis." (PMID 28056026, 2017). "The kinases MAPKAPK2, RPS6KB1 and RPS6KA3 were more often regulated in the noncancer conditions when compared to their degree of regulation in tumours." (PMID 36688815, 2023).
cancer (469 papers, 2000 to 2026). A tumor composed of atypical neoplastic, often pleomorphic cells that invade other tissues. "Furthermore, due to the association between RPS6KB1 amplifications and cancer, there has been considerable interest in the development of inhibitors of S6K1, such as LYS6K2 and PF-4708671." (PMID 32054043, 2020). "Here, we report a patient with a high-grade malignant neoplasm, most compatible with carcinoma, involving the lung and mediastinum in which we identify a novel CLTC::RPS6KB1 fusion as the likely driver mutation." (PMID 40091373, 2025). "RPS6KB1 is a ribosomal serine/threonine kinase that induces cell growth and proliferation and potentiates survival of some cancer subtypes (94, –, 98)." (PMID 41165329, 2025). "These efforts led to the identification of two additional tumors with ADK::KAT6B rearrangement and one carcinoma carrying RPS6KB1::VMP1 fusion." (PMID 40661875, 2025). "These 17 translocations were further analyzed in 1,059 mutation-negative NSCLCs, which resulted in the identification of two additional tumors with ADK::KAT6B rearrangement and one carcinoma carrying RPS6KB1::VMP1 fusion." (PMID 40661875, 2025). "The most frequently observed fusion partner of VMP1 is RPS6KB1, identified in multiple cancer types." (PMID 38612567, 2024). "High levels of RPS6KB1 and low levels of miR-30e closely correlated poor survival of patients with several other types of cancer." (PMID 34727092, 2021). "A comparison of alteration frequencies between RPS6KB2 and RPS6KB1 in the TCGA pan-cancer dataset showed similar patterns, with amplification being the most common alteration across cancers, such as breast, endometrial, esophagogastric, ovarian, and bladder cancers." (PMID 39796034, 2024). "Growing evidence shows that RPS6KB1 overexpression/activation is a critical driver of initiation and progression of tumors, and that the inactivation of RPS6KB1 may be therapeutically effective in many types of cancer." (PMID 34727092, 2021). "In a wide variety of cancers, RPS6KB1 is regulated by Akt/mTOR signaling pathway." (PMID 28792981, 2017). "Mechanistically, loss of PAK1 promoted mRNA decay and inhibited the expression of CD44, SAA1, MTOR, RPS6KB1, and EIF4G1, the factors involved in tumorigenesis in many cancers." (PMID 41459112, 2026). "Understanding the molecular biology of WIP1 inhibitors could increase the potency of WIP1 inhibitors in a specific subsets of tumors with PPM1D/RPS6KB1 and ERBB2 co-amplification that may lead to improved cancer care." (PMID 31827209, 2019). "Although previous studies have shown that EVA1A regulates autophagy through ATG5 and mTOR/RPS6KB1 pathways in cancer, the mechanism of EVA1A regulating autophagy in cancer is not completely clear and needs to be further clarified." (PMID 35743108, 2022).
infection (78 papers, 2012 to 2025). The state of being infected such as from the introduction of a foreign agent such as serum, vaccine, antigenic substance or organism. "Moreover, kinases found to be upregulated by the infection of HIBCPP cells with both N. meningitidis strains in this analysis (downregulated in control cells) include MAPKAPK2, RPS6KB1, RET as well as AKT1 and AKT2, whereas PRKACA activity was upregulated only by MC58siaD." (PMID 37065199, 2023).
psychiatric disease (2 papers, 2021 to 2024). "Pten (Chr 19 male Hypothermia QTG), Rps6kb1/p70S6K (Chr 11 Mobility and male Hypothermia QTG), and Pde4d (Chr 13 female Hypothermia QTG) were the most well connected QTGs in terms of associations with drugs of abuse and psychiatric disease." (PMID 34367237, 2021).
RPS6KB1 also shares sentences with these, for which no sentence is quoted: ovarian carcinoma (79 papers); glioma (54); colon carcinoma (46); colorectal cancer (40); cervical carcinoma (37); diabetes (35); depression (22); liver cancer (21); leukemia (20); Glucose intolerance (14); Hyperglycemia (14); metabolic disease (13); type 2 diabetes (13); viral infection (13); liver fibrosis (12); colitis (11); Hyperinsulinemia (11); diabetic nephropathy (10); metabolic syndrome (10); Sepsis (10); Alzheimer disease (9); invasive breast carcinoma (9); multiple myeloma (9); triple-negative breast carcinoma (9); Cachexia (8); cyst (8); heart failure (8); myocardial infarction (8); autism (7); Cerebral ischemia (7).
A further 279 diseases each share a sentence with RPS6KB1 in 7 papers or fewer.